PLCB1 (phospholipase C beta 1)
Description:
Catalyzes the hydrolysis of 1-phosphatidylinositol 4,5-bisphosphate into diacylglycerol (DAG) and inositol 1,4,5-trisphosphate (IP3) and mediates intracellular signaling downstream of G protein-coupled receptors. Regulates the function of the endothelial barrier.
Synonyms: PLC-I; PLC-beta-1; KIAA0581; PLC154; DEE12; EIEE12; PI-PLC; PLC-154; PLCB1A; PLCB1B; LOC105372522
Tractability: Antibody: the Human Protein Atlas places it where antibodies can reach. PROTAC: ubiquitination databases record sites on it; its protein half-life has been measured.
Target class: Enzyme
Gene: Protein-coding gene on chromosome 20 (8,077,251 to 8,968,360, forward strand). Ensembl gene ENSG00000182621.
Subcellular location: Nucleus membrane; Cytoplasm
Subcellular location (Human Protein Atlas): Plasma membrane
Pathways (Reactome):
Signal Transduction: Ca2+ pathway; G alpha (q) signalling events; G beta:gamma signalling through PLC beta; PLC beta mediated events
Metabolism: Acetylcholine regulates insulin secretion; Fatty Acids bound to GPR40 (FFAR1) regulate insulin secretion; Synthesis of IP3 and IP4 in the cytosol
Neuronal System: Presynaptic function of Kainate receptors
Gene Ontology:
Molecular function: calmodulin binding; enzyme binding; GTPase activator activity; phosphatidylinositol-4,5-bisphosphate binding; phosphatidylinositol-4,5-bisphosphate phospholipase C activity; protein binding; identical protein binding; phosphatidylinositol phospholipase C activity; phospholipase C activity; calcium ion binding; lamin binding; phosphoric diester hydrolase activity
Biological process: interleukin-1-mediated signaling pathway; interleukin-12-mediated signaling pathway; interleukin-15-mediated signaling pathway; phosphatidylinositol metabolic process; positive regulation of JNK cascade; activation of meiosis involved in egg activation; cerebral cortex development; G protein-coupled acetylcholine receptor signaling pathway; G protein-coupled receptor signaling pathway; G2/M transition of mitotic cell cycle; glutamate receptor signaling pathway; insulin-like growth factor receptor signaling pathway; memory; negative regulation of DNA-templated transcription; negative regulation of monocyte extravasation; phosphatidylinositol-mediated signaling; positive regulation of acrosome reaction; positive regulation of developmental growth; positive regulation of DNA-templated transcription; positive regulation of embryonic development; positive regulation of G1/S transition of mitotic cell cycle; positive regulation of glycoprotein biosynthetic process; positive regulation of interleukin-12 production; positive regulation of myoblast differentiation; regulation of fertilization; and 21 more
Cellular component: cytoplasm; extracellular exosome; nuclear speck; chromatin; cytosol; nuclear membrane; nucleus; GABA-ergic synapse; glutamatergic synapse; postsynaptic cytosol; protein-containing complex
Genetic constraint (gnomAD): Loss-of-function variants: 22 observed, 88.06 expected, observed/expected ratio (o/e) 0.25, 90% interval 0.18 to 0.36. The upper end of that interval is the gene's LOEUF score, 0.36, which puts it in group 1 of 6, group 1 being the genes least tolerant of losing a copy. Missense variants: 699 observed, 1,024 expected, observed/expected ratio (o/e) 0.68, 90% interval 0.64 to 0.73. Synonymous variants: 364 observed, 363.57 expected, observed/expected ratio (o/e) 1, 90% interval 0.92 to 1.09.
Gene-disease validity (ClinGen):
ClinGen rates the evidence that PLCB1 causes each of these diseases.
genetic developmental and epileptic encephalopathy (autosomal recessive): Definitive. A complex neurodevelopmental disorder characterized by a range of developmental delays and epileptic encephalopathy phenotypes.
Homologues: Orthologues: chimpanzee PLCB1 (100% identical), macaque PLCB1 (99% identical), dog PLCB1 (98% identical), rabbit PLCB1 (98% identical), guinea pig PLCB1 (98% identical), pig PLCB1 (98% identical), mouse Plcb1 (97% identical), rat Plcb1 (97% identical), tropical clawed frog plcb1 (86% identical), zebrafish plcb1 (55% identical), Drosophila melanogaster Plc21C (41% identical), Caenorhabditis elegans plc-3 (20% identical), and 3 more. Paralogues in human: PLCB3 (55% identical), PLCB2 (45% identical), PLCB4 (38% identical), PLCE1 (25% identical), PLCH2 (23% identical), PLCH1 (22% identical), PLCL2 (22% identical), PLCL1 (22% identical), PLCG2 (21% identical), PLCD4 (21% identical), PLCG1 (19% identical), PLCD1 (19% identical), and 2 more.
Diseases named in the same sentence as PLCB1 in open-access papers:
PLCB1 is named in the same sentence as 120 diseases in open-access papers, as found by Europe PMC text mining. Sharing a sentence is not in itself a finding about the gene and the disease. The quoted sentences say what the papers report.
schizophrenia (24 papers, 2010 to 2025). A major psychotic disorder characterized by abnormalities in the perception or expression of reality. "Several studies have linked PLCβ1 with brain disorders, such as epileptic seizure, depression, and schizophrenia in the cortex." (PMID 38959322, 2024). "PLCB1 dysregulated signaling is linked to several brain disorders, including epilepsy, schizophrenia, bipolar disorder, Huntington’s disease, depression and Alzheimer’s disease." (PMID 37063368, 2023). "PLCB1 has been linked to several diseases, including schizophrenia, epileptic encephalopathy, and myotonic dystrophy." (PMID 36611865, 2022). "The gene PLCB1 plays an important role in signal transduction from G-protein coupled receptors (GPCRs), which have been associated with risk of developing schizophrenia in humans." (PMID 31783652, 2019). "Phospholipase C beta 1 (PLCB1) is a rate-limiting enzyme for downstream signalling of several neurotransmitter systems implicated in the pathophysiology of schizophrenia (Sz)." (PMID 28560265, 2017). "Plcb1 is of critical importance in codifying neurotransmitter receptors and is associated with schizophrenia." (PMID 24555847, 2014). "The strongest evidence of association with a diagnosis of schizophrenia was in PLCB1 (20p12.3) (rs6108205, P≈1.00×10−3, intermediate Scz diagnosis)." (PMID 22220189, 2011). "Although the disruption of PLCβ1-mediated signaling in the brain is associated with epilepsy, schizophrenia, and bipolar disorder, to the best of our knowledge, our results provide the first direct evidence of the disruption of the hippocampal PLCβ1 pathway in a rodent model of AD." (PMID 34625112, 2021). "In addition, multiple deletions and duplications of ≥480 kb were found to be enriched in individuals with ASD compared to controls, and other rare deletions within PLCB1 have been linked to early-onset epileptic encephalopathy and schizophrenia." (PMID 24564958, 2014). "With adequate refinement of the probing technique and more data on PLCB1 mutations in schizophrenia, even a more accurate premorbid prediction might be possible." (PMID 25566074, 2014). "Interestingly, regional differences in phospholipase C isoenzyme (Plcb1, Plcb4), druggable targets identified in the Camk2a proteome, expression in the brain are known to underlie several brain disorders including epilepsy, schizophrenia, and AD47." (PMID 35614064, 2022). "Changes in PLCB1 could provide a marker for suicide risk in schizophrenia." (PMID 28560265, 2017). "PLCB1 plays multiple biological roles in human diseases, such as inflammation, cell proliferation, and schizophrenia." (PMID 36134029, 2022). "PLCβ-1-knockout mice exhibit a schizophrenia-like phenotype, with an increased incidence of adult hippocampal neurogenesis, and deletions of PLCβ-1 have been observed in the orbitofrontal cortex of patients with schizophrenia." (PMID 34361045, 2021). "However, phospholipase C beta 1 protein has also been shown to be lower in Brodmann’s area 8 and 9 from teenage suicide subjects, creating a potential confound in interpreting the findings in schizophrenia due to the high suicide rate associated with this disorder." (PMID 28560265, 2017). "Madhara Udewela at the Florey Institute, Australia, and co-workers measured post-mortem levels of two PLCB1 variants (a and b) in two areas of the prefrontal cortex (BA9 and BA46) in schizophrenia, many of whom were suicide completers." (PMID 28560265, 2017). "Our previous study demonstrated that phospholipase C beta 1 mRNA was down-regulated in Brodmann’s area 46 from subjects with schizophrenia." (PMID 28560265, 2017). "In this RMTA paradigm, we compared performances of wild-type (PLCβ1+/+) mice and phospholipase C β1 knock-out (PLCβ1-/-) mice which are known as one of the genetic models for schizophrenia." (PMID 26731530, 2016).
schizophrenia (continued). "The present study with PLCβ1-/- mice has shown, using a well-defined minimal amount of odor-taste training, the first genetic mouse model of schizophrenia that displays impaired reality testing with an abnormal phenomenon of “persistent” RMTA." (PMID 26731530, 2016). "PLCβ1-/- mice are known to be one of the genetic mouse models for schizophrenia, displaying relevant behavioral phenotypes including, deficit in sensorimotor gating, hyperactivity, abnormal social behaviors, and impaired working memory." (PMID 26731530, 2016). "PLCB1 KO mice display typical endophenotypes for schizophrenia and reduced levels of M1 receptor binding." (PMID 25566074, 2014). "The most significant SNPs resided in ROR1 and PLCB1, genes known to be involved in bipolar disorder and schizophrenia, respectively." (PMID 21494683, 2011). "Furthermore, PLCB1 has previously been related to other psychiatric and neurological disorders such as schizophrenia, autism and epilepsy." (PMID 28860459, 2017). "Consistent with our previous study, levels of phospholipase C beta 1 a and b mRNA, but not protein, were lower in Brodmann’s area 46 from subjects with schizophrenia." (PMID 28560265, 2017).
breast carcinoma (17 papers, 2016 to 2025). "PLCB1 is also involved in the cell cycle and cell proliferation and is associated with breast cancer and colorectal cancer." (PMID 36611865, 2022). "Furthermore, increased expression of both PTPRN2 and PLCB1 associated with significantly worse overall survival and worse distal metastasis‐free survival in two large breast cancer patient cohorts." (PMID 26620550, 2016). "Another protein ERα-regulated protein from TGFα-EGFR is PLCB1 which was recently identified as a metastatic breast cancer driver gene." (PMID 35290621, 2022). "PLCB1 was identified as a malignant cell-specific genes in HCC, and has been reported to be implicated in breast cancer, HCC, and ovarian cancer." (PMID 35707353, 2022). "There were seven shared hub nodes (FPR2, CXCR4, FPR1, CX3CL1, GPR37, GABBR2 and PLCB1) between metastatic breast cancer cell lines." (PMID 35045088, 2022). "Overexpression of both PTPRN2 and PLCβ1 further increased the migratory capacity of breast cancer cells to a greater extent than overexpression of either gene alone." (PMID 26620550, 2016). "Both PTPRN2 and PLCβ1 also demonstrated localization to the plasma membrane in breast cancer cells, in addition to some cytoplasmic localization (Fig EV3A)." (PMID 26620550, 2016). "Our results identify PLCβ1 as an alternative path of cofilin activation in breast cancer—distinct from the route of activation previously ascribed to PLCγ1." (PMID 26620550, 2016). "To investigate the clinical significance of these genes, we quantified the expression levels of PTPRN2 and PLCβ1 in primary tumor cDNA samples derived from patients diagnosed with various stages of breast cancer." (PMID 26620550, 2016). "Knockdown of PTPRN2 or PLCβ1 in four other breast cancer cell lines (BT‐549, CNLM1a, HCC‐1806, and MDA‐MB‐468) also significantly reduced the migratory capacity of these cells." (PMID 26620550, 2016). "Furthermore, PLCB1 has been identified as an oncogenic driver, in cholangiocarcinoma, breast cancer, hepatocellular cancer, and gastric cancer." (PMID 40278994, 2025). "PLCβ1 was shown to be involved in breast cancer, and there are significant differences in PLCβ1 expression between metastasized and recurrent tumor tissue, highlighting its role in promoting migration in breast cancer." (PMID 37370855, 2023). "Furthermore, PLCβ1 has been reported to participate to the migratory or metastatic potential of different cancer types, including breast cancer." (PMID 35303162, 2022). "PLCB1, Phospholipase C Beta 1, has been also reported that lead to breast cancer development." (PMID 33962648, 2021). "PLCB1 has been recently shown to promote breast cancer metastasis." (PMID 32143622, 2020). "Interestingly, expression levels of PTPRN2 and PLCB1 are significantly positively correlated in primary tumors from a cohort of breast cancer patients." (PMID 26620550, 2016). "The high expression of PLCB1 was also shown to be related to the development and poor prognosis of various cancers, including hepatocarcinoma, colorectal cancers, non-small cell lung carcinoma, breast cancer, and acute myeloid leukemia, suggesting its oncogenic role in different cancers." (PMID 34064422, 2021). "Protein-protein interaction (PPI) analysis revealed seven shared (PLCB1, FPR1, FPR2, CX3CL1, GABBR2, GPR37, and CXCR4) hub genes between brain and lung metastasis in breast cancer." (PMID 35045088, 2022). "To further test the ability of PTPRN2 and PLCβ1 to promote metastasis, we overexpressed these genes in the less metastatic MDA parental breast cancer cells (Fig EV2F and G)." (PMID 26620550, 2016). "To functionally test their roles in breast cancer metastasis, we depleted PTPRN2 and PLCβ1 in highly metastatic LM2 cells and performed tail vein metastatic colonization assays." (PMID 26620550, 2016).
breast carcinoma (continued). "Increased expression of PLCB1 and PTPRN2 correlates with worse overall survival and distal metastasis‐free survival in breast cancer patients, further underscoring the clinical relevance of these findings." (PMID 26620550, 2016). "Additionally, our study explored the roles of other hub genes, including BCL2, PLCB1, ADCY1, and GNAO1, within the HER2-positive breast cancer context." (PMID 39682150, 2024). "Given the changes in cofilin localization and its activity observed upon PLCβ1 and PTPRN2 modulation, we next asked whether these changes in CFL1 localization alter the actin cytoskeleton in breast cancer cells." (PMID 26620550, 2016). "The role for PLCβ1 in breast cancer metastasis has not been previously reported; however, PLCB1 has been identified to be upregulated in colorectal cancer as well." (PMID 26620550, 2016).
epilepsy (14 papers, 2011 to 2024). A brain disorder characterized by episodes of abnormally increased neuronal discharge resulting in transient episodes of sensory or motor neurological dysfunction, or psychic dysfunction. "Together, these findings implicate that the PLCB1 gene contributes to the genetic risk of neurodevelopmental disorders including epilepsy." (PMID 25950944, 2015). "Mutations in Cdh8 and Plcb1 are associated with susceptibility to autism and the development of early-onset epilepsy, respectively." (PMID 22103416, 2011). "Thus, single case reports of deletions in chromosome 20p12.3 that disrupts PLCB1 and compound heterozygous gene mutations were implicated in intractable early infantile epilepsy." (PMID 25566074, 2014). "Previous studies found that PLCβ1 null-knockout mice exhibited epilepsy, hyperlocomotion, startle response, abnormal social ability, and deficits in fear." (PMID 38959322, 2024). "As a result, abnormal PLCβ1 expression has been studied for its role in neurological diseases extensively such as seizure and epilepsy." (PMID 26614510, 2016). "Microdeletions found only in GGE patients harboured a high proportion of genes previously associated with epilepsy and neuropsychiatric disorders (NRXN1, RBFOX1, PCDH7, KCNA2, EPM2A, RORB, PLCB1)." (PMID 25950944, 2015). "PLCβ1 knockout mice are afflicted with epilepsy while abnormal activity and expression level of PLCγ1 are detected in pathologies including Huntington's disease, depression and Alzheimer's disease." (PMID 25875657, 2015). "Moreover, several studies have shown a connection between PLCβ1 and brain disorders such as epilepsy and psychiatric disorders involving the cortex." (PMID 38959322, 2024). "This may suggest that, although CACNA1A contributes to epilepsy mutational load, the noise from other pathway-related genes (CHRNA4, KCNQ2, KCNQ3 and PLCB1) compromises this effect." (PMID 27984588, 2016). "These microdeletions affected 158 protein-coding RefSeq genes and exhibited an enrichment of genes previously associated with epilepsy (NRXN1, RBFOX1, PCDH7, KCNA2, EPM2A, RORB, PLCB1) and neuropsychiatric disorders (DPYD, CADM2, PARK2, GRM8, TSNARE1, TPH2, MACROD2)." (PMID 25950944, 2015). "In conclusion, we report a novel case of PLCB1-EIEE in an child presenting with developmental delay and epilepsy." (PMID 24684524, 2014).